IL6 (interleukin 6)
Diseases named in the same sentence as IL6 in open-access papers (continued):
Sharing a sentence is not in itself a finding about the gene and the disease.
influenza (continued). "The same cytokines were shown to be elevated in infected individuals during the influenza pandemic in 2009 where expression of IL-12p70, IL-6 and IL-15 correlated with severe clinical outcome, although co-infection with SP was not confirmed in that study." (PMID 23421931, 2013). "Otherwise, in older stressed or chronically depressed adults, an increase in inflammatory response occurs when they are challenged with antigens, showing depressive characteristics and elevated levels of IL-6 after immunization with influenza vaccines." (PMID 23935250, 2013). "IL-6 is an important cytokine that orchestrates the acute-phase response to inflammation and actually contributes to the febrile response to influenza and other infections, via phosphorylation of STAT3 (signal transducer and activator of transcription 3)." (PMID 24116168, 2013). "In particular, levels of cytokines IL-6 and TNF-α were reported to be positively correlated with influenza associated lethality." (PMID 24124485, 2013). "The analysis of a cohort of 160 healthy university students showed that CMV-seropositive individuals had a reduction in their CD4:CD8 ratio, an increase of EMRA T cells, elevated plasma IL-6 and lower response to influenza vaccination." (PMID 23114110, 2012). "IL-6 exhibits pleiotropic effects, including the activation of NK cells and macrophages and stimulation of T cell differentiation during influenza infection." (PMID 22792270, 2012). "Plasma levels of IL-6, IL-8, MCP-1 and IFNγ were significantly increased in swine H2N3 compared to human H2N2 infected animals supporting the previously published notion of increased IL-6 levels being a potential marker for severe influenza infections." (PMID 22808082, 2012). "Further investigation is critical to elucidate the role of IL-6 as a disease severity marker in influenza, specifically severe H1N1pdm." (PMID 22679491, 2012). "In the context of influenza infections, IL-6 is a key cytokine important for regulating the shift from innate to adaptive components of the antiviral immune responses, including proliferation of T cells and influenza-specific memory T cells." (PMID 20920950, 2011). "IL-6 is a cytokine that is a primary mediator of inflammatory response in influenza infection, and is involved in driving the hypercytokinemia response in VN1203 infection." (PMID 22074594, 2011). "PBMCs in seasonal influenza patients were activated and expressed cytokines ex vivo (e.g. IL-6, CXCL8/IL-8, CCL2/MCP-1, CXCL10/IP-10, CXCL9/MIG); their ‘responsiveness’ to stimuli was shown to change dynamically during the illness course." (PMID 22022504, 2011). "Of these, IL6 is a known marker of influenza disease severity with probable involvement in tissue damage." (PMID 20957032, 2010). "The treatment induced expression of the inflammatory cytokines IL-6 and TNF in bronchoalveolar lavage fluid 8- and 40-fold greater, respectively, than that caused by lethal influenza infection." (PMID 19137067, 2009). "In this respect, depletion of CD25+ cells had a variable affect on proliferative responses observed in WT mice, removal of CD25+ cells uncovered influenza-specific memory CD4+ T cell responses in the majority of IL-6−/− mice." (PMID 18389078, 2008). "This experiment revealed that influenza-specific proliferative responses can be detected in IL-6−/− mice and suggest that these responses, and to a lesser extent, responses in WT mice, are subject to suppression by Tregs." (PMID 18389078, 2008). "This study explored the impact of a cytokine, interleukin-6 (IL-6), on generation of effective influenza-specific T cell memory." (PMID 18389078, 2008). "In this study we compared influenza-specific CD4+ and CD8+ T cell memory after infection of wild-type (WT) and IL-6 deficient (IL-6−/−) C57BL/6 (B6) mice with influenza virus." (PMID 18389078, 2008).
influenza (continued). "The impact of IL-6 on the influenza-specific T cell response appears to be selective for CD4+ T-cells implying that IL-6 has a different effect on the behavior of CD4+ and CD8+ T cells." (PMID 18389078, 2008). "We demonstrate that influenza-induced IL-6 limits the activity of virus-specific Tregs, thereby facilitating the activity of virus-specific memory CD4+ T cells." (PMID 18389078, 2008). "We were unable to detect a greater increase in the number of Tregs (by Foxp3 staining) in the lymph nodes or spleens of influenza-infected IL-6−/− compared to WT mice." (PMID 18389078, 2008). "More influenza-specific proliferation was observed in the cultures from WT mice than IL-6−/− mice and a higher percentage of these cells produced IFNγ." (PMID 18389078, 2008). "However, in this study, we demonstrate that deletion of IL‐6 during influenza infection preserves host immunity against secondary aspergillus infection." (PMID 40420617, 2025). "However, short-term (<7 days) exposure can lead to reduced IL-6 production, subsequently compromising the immune response, and diminishing influenza resistance in mice." (PMID 40291836, 2025). "A deeper understanding of IL-6 regulation within the innate immune response could offer critical insights for improving treatment strategies for influenza infections." (PMID 40692679, 2025). "IL‐6 deficiency did not alter weight loss, inflammatory cell recruitment, or bacterial burden during post‐influenza MRSA pneumonia." (PMID 39921246, 2025). "The levels of GMP, IMP and AMP were positively correlated with the disease severity and the peripheral level of IL-6 and TNF-ɑ, with GMP exhibiting the most relevance, which indicated the potential of nucleotide metabolites in diagnosing influenza-associated pathologies." (PMID 40517177, 2025). "Cytokine analysis revealed a distinct immunological pattern in pregnant women infected with influenza, characterized by the simultaneous elevation of both pro-inflammatory (IL-6, IFN-γ) and anti-inflammatory (IL-10) mediators; this finding challenges the conventional Th1/Th2 paradigm." (PMID 40558593, 2025). "Targeting of such host factors involved in IAV-induced IL-6 regulation may hold promising therapeutic strategy in the treatment of influenza." (PMID 40692679, 2025). "Future studies are warranted to determine how IL‐6 inhibition, versus total deletion, may affect influenza infection or post‐influenza bacterial pneumonia." (PMID 39921246, 2025). "First, we measured IL‐6 levels in mice infected with singular aspergillus, singular influenza, and dual infected with both influenza and aspergillus and observed increased levels of IL‐6 in both influenza‐infected and dual‐infected mice compared to mice infected with aspergillus alone." (PMID 40420617, 2025). "Artemisinin-derived artesunate (ART) significantly reduces the expression of TNF-α, IL-6, and IL-1β in the lung tissue of influenza-infected mice by inhibiting the TLR4/NF-κB (p65) axis, with a lung index reduction of over 30%, and significantly improves body weight and survival rate." (PMID 40860873, 2025). "Additionally, IL‐6 protects neutrophils from influenza‐mediated apoptosis and lung epithelial cells from influenza‐mediated apoptosis." (PMID 40420617, 2025). "Influenza infection triggers an intense systemic inflammatory response characterized by the release of pro-inflammatory cytokines such as interleukins (IL-1, IL-6, IL-8), tumor necrosis factor-alpha, and interferons, which activate inflammatory cells within atherosclerotic plaques." (PMID 40499619, 2025). "Similarly, influenza-induced monocyte-derived AMs (Mo-AMs) can contribute to bacterial defense through IL-6-mediated mechanisms." (PMID 40748050, 2025). "Furthermore, ELISA results demonstrated that AAV6-GFP-HO-1 effectively inhibited the production of pro-inflammatory cytokines in lung tissue following influenza infection, specifically IL-6, MCP-1, and granulocyte-macrophage colony-stimulating factor (GM-CSF)." (PMID 40160414, 2025).
influenza (continued). "Additionally, because IL‐6 inhibitory therapies have improved outcomes during COVID‐19, we evaluated the impact of IL‐6 deletion on post‐influenza MRSA pneumonia." (PMID 39921246, 2025). "IL-6 has a dual role in influenza infections, exerting both protective and detrimental effects." (PMID 40692679, 2025). "Moreover, the expression of Oas1a/g, Irf7, and Il6, that are involved in the immune response to influenza infection, was elevated in lungs." (PMID 41567998, 2025). "Findings presented here may be relevant to therapeutic modalities being used to target IL‐6 signaling, which have been used to treat patients with COVID‐19 and have been proposed to be utilized during influenza infection." (PMID 40420617, 2025). "Importantly, Spring PM exposure prior to influenza infection increased release of several cytokines as measured at 24 h p.i. which are indicative of cytokine storm in influenza infection: IL-6, IL-8, IL-10, and MCP-163–64." (PMID 40671793, 2025). "aQIV-vaccinated mice also had no increase in influenza-associated inflammatory cytokines like IL-1β, TNFα, IL-2, and IL-6." (PMID 39975920, 2025). "IL-6 knockout animal models indicate that IL-6 depletion impairs both innate and adaptive immune responses, leading to increased morbidity and mortality during influenza infection." (PMID 40692679, 2025). "A deeper understanding of IAV-induced IL-6 production and signaling could inform the development of targeted therapies to more effectively manage influenza." (PMID 40692679, 2025). "Given the beneficial effects of IL‐6 observed during both singular influenza and singular aspergillus infection, we hypothesized that IL‐6 deletion would result in defective host immunity and increased morbidity and fungal burden during IAPA." (PMID 40420617, 2025). "In response to influenza viral entry, epithelial and immune cells induce pro-inflammatory cytokines and chemokines such as interleukin-1β, interleukin-6, tumor necrosis factor α (TNFα), CCL2, CCL3, and CCL5, which recruit macrophages and neutrophils to the site of infection to control the virus." (PMID 39846844, 2025). "The role of IL‐6 during IAPA remains unclear and increased understanding is critical prior to the use of immunomodulatory therapies targeting IL‐6 during influenza infection." (PMID 40420617, 2025). "We found that IL‐6 deficiency does not alter weight loss at day 7 post‐influenza MRSA pneumonia compared to wild‐type (WT) mice." (PMID 39921246, 2025). "QIV also showed higher cytokine levels associated with influenza-induced inflammation, such as IL-1β, TNFα, IL-2, and IL-6, similar to the PBS group, which did not control viral replication well." (PMID 39975920, 2025). "During singular influenza infection, increased TNFα and increased TNFα production by monocytes was observed in the airways of IL‐6 deficient mice, whereas we saw no changes during IAPA." (PMID 40420617, 2025). "We observed that IL‐6 deficiency did not impair the host's ability to defend against post‐influenza MRSA pneumonia." (PMID 39921246, 2025). "The pathogenesis of IAE has not yet been determined, and the “cytokine storm hypothesis,” which states that a large number of IL-6 and other cytokines in children with influenza promote the occurrence of IAE, is widely accepted internationally." (PMID 39624480, 2024). "Malic acid showed strong negative associations with TNFα, IL-6, and IL-1β cytokine levels upon influenza stimulation." (PMID 39331702, 2024). "Elevated IL-6 is also a predictor of intensive care unit admission in influenza patients." (PMID 39624480, 2024). "Not only did this study show that IL-6 was required for optimal activation of influenza-specific T-cell responses, but also that this cytokine was necessary for controlling viral load, and for limiting the excessive recruitment of damaging inflammatory monocytic cells to the lungs." (PMID 38255717, 2024). "IL-6 can be used to predict the severity of illness or death in influenza patients." (PMID 39624480, 2024).
influenza (continued). "Viremia may induce expression of IL-6 by fetal membranes and chorion, for example, in influenza infection." (PMID 37685739, 2023). "Whether this reflected reduced neutrophil infiltration or longevity has not been established yet; however, this reduction correlated with a further reduction in IL‐6, a cytokine that can protect neutrophils from influenza‐induced cell death." (PMID 36969366, 2023). "Flu-IVIG treatment decreases serum concentration of IL-6 in patients with severe influenza." (PMID 37289541, 2023). "In the context of influenza, LANCL2‐deficient mice have higher levels of IL‐6 and MCP‐1 in their lungs, while the oral treatment of infected mice with selective LANCL2 ligands abscisic acid and NSC61610 reduced the levels of TNF and MCP‐1 in the lung during IAV infection." (PMID 36969366, 2023). "Increased levels of IL-6 are directly correlated to influenza symptoms." (PMID 36180831, 2022). "Importantly, inhibition of IL-6 by the suppressor of cytokine signaling 3 (SOCS-3) improves influenza outcomes by reducing inflammation in mice (Liu and others 2019)." (PMID 35674675, 2022). "IFITM3 also restricts IL-6 production in response to influenza and SARS-CoV-2." (PMID 36075894, 2022). "Moreover, IFN-γ, IL-2, and IL-6 production in response to influenza protein was markedly increased in aged mice, similar to that observed in young mice." (PMID 34099809, 2021). "Furthermore, a longitudinal study of 151 children with viral URI showed that elevated concentration of IL-6 correlated with fever and was significantly higher during influenza and adenovirus infection compared with enterovirus and HRV." (PMID 35096705, 2021). "Heat-killed L. casei DK128 shows similar anti-inflammatory effects against influenza infection by decreasing influenza virus-induced pro-inflammatory cytokines (IL6 and TNF-α), monocytes, and activated NK cells in the lungs of mice, thereby preventing pulmonary inflammation." (PMID 33897683, 2021). "Interstitial macrophages are known to secrete IL-1, IL-6, and TNF-α and thus, could play a pathogenic role during S. pneumoniae-influenza superinfection." (PMID 33690728, 2021). "We also conducted multiplex measurement on cytokines and chemokines at day 7 p.i. in lung tissues using Luminex 200, and similarly, we found significantly higher production of IL-1β, IL-6, TNF-α, IL-10, MCP-1, IP-10, and IFN-γ caused by influenza infection on day 7 p.i.." (PMID 35154087, 2021). "IL-6 may be considered a potentially useful biomarker for influenza testing, and its significance as a biomarker may be further underscored by its associated rise in patients with encephalopathy." (PMID 34692664, 2021). "In addition, influenza vaccination was followed by a modified pro/anti-inflammatory balance in the IL-1 pathway, with lower IL-1β and IL-6, but higher IL-1Ra response after SARS-CoV-2 stimulation in vitro." (PMID 34695164, 2021). "The significant up-regulated IL-6 and CRP level were observed in severe influenza (especially H1N1category) and were linked to severe tissue and organ damage and to the likelihood of developing more severe clinical manifestations, respiratory failure and complications, as well as poorer outcome." (PMID 33537328, 2020). "Despite improvement in inflammatory cytokine production by Pneumovax, these outcomes were directly impacted by influenza, with significantly higher levels of IL-6 mRNA and cytokine production being detected in aged lung during secondary S. pneumoniae infection." (PMID 32545261, 2020). "In adult mice, IL-6 can enhance T-cell mediated antibody response against i.m. influenza immunization and there is evidence supporting the importance of IL-6 in the early response to influenza infection." (PMID 33193346, 2020). "Also, it has been shown that levels of IL-2, IL-6, IL-18, TNFα, IFNγ, ET-1, sICAM-1, and sVCAM-1 are increased in influenza-infected MI patients." (PMID 33193350, 2020).
influenza (continued). "Furthermore, IL-6 and IL-1 are the crucial pro-inflammatory cytokines produced by the host during influenza infection." (PMID 32269562, 2020). "More studies are needed to determine whether the bioactive lipid products of ALOX8 can modulate inflammatory responses toward influenza infections directly or through modulating the expression of cytokines IL-6 and KC." (PMID 31013822, 2019). "IL-6 has been shown to be important during influenza pathogenesis in the lungs." (PMID 32038632, 2019). "This study evaluated whether IL-6 had an important role in resisting secondary bacterial infections post influenza infection." (PMID 32038632, 2019). "Thus, treatment of influenza-infected WT mice with a single dose of IL-6 at the time of S. pneumoniae challenge is effective against secondary pneumococcal pneumonia, but can't effectively change the survival of co-infected mice." (PMID 32038632, 2019). "CoQ10 levels in influenza patients also had a significant although weak correlation with several inflammatory biomarkers, though not with others which have been implicated in influenza pathogenesis (IL‐6)." (PMID 30156030, 2019). "In a human challenge model of influenza, IL-6, IL-15, and MCP-1, among others, were highly upregulated in the first several days post-challenge in subjects who later developed symptoms; while serum samples from subjects with no symptoms post-challenge did not have elevations of these cytokines." (PMID 30557313, 2018). "Although IL-6 is an important inflammatory cytokine in the initial phase of influenza viral eradication, it has been found to be highly elevated in plasma and hyperactivated from peripheral blood mononuclear cells of patients with complicated viral influenza infection." (PMID 29890620, 2018). "Therefore, we demonstrate that IL-6 not only acts as an immune regulator for defending against influenza, but also plays an important role in balancing lung environment." (PMID 28262742, 2017). "Physiological analysis of sickness behavior of mice following influenza infection revealed that virus-associated body temperature and motor activity decreases were significantly attenuated in mice lacking IL-6, compared to wild-type infected mice." (PMID 28900138, 2017). "Anti-IL-6R treatment may diminish influenza vaccine antibody responses since IL-6 induces B cell differentiation into antibody-forming cells and T cells into effectors cells." (PMID 28784185, 2017). "Here, we studied the role of IL-6 in acute influenza infection in mice." (PMID 28262742, 2017). "Collectively, these results suggest that presence of IL-6 may promote the migration and recruitment of macrophages to the lung and reduce their death during influenza infection." (PMID 28262742, 2017). "Other mouse models support the idea of a protective role of IL6 in influenza infections." (PMID 29038764, 2017). "To study the role of endogenous IL-6 in host defense against influenza, we compared the body weight change and survival curves, as well as histological and immunological changes between IL-6-deficient (IL-6−/−) and WT C57BL/6 mice after intranasal infection of influenza A/WSN/33 (H1N1) virus (IAV)." (PMID 28262742, 2017). "In the present study, we demonstrate that IL-6 plays a critical role in promoting lung repair in mice with influenza infection through participating in the interplay of macrophages, fibroblasts and lung epithelial cells, as well as through inhibiting TGF-β production." (PMID 28262742, 2017). "Furthermore, when we compared nasal wash samples from influenza-infected patients with viral load ≥ 28 and increased IL-6 and CXCL10 to healthy controls, we identified 162 differentially-expressed proteins between the two groups." (PMID 27088501, 2016). "As found in other studies, our studies further confirm that IL-6 may serve as an important marker for severe complications following influenza infection." (PMID 27110056, 2016).